EGFR (epidermal growth factor receptor)
Diseases named in the same sentence as EGFR in open-access papers (continued):
Sharing a sentence is not in itself a finding about the gene and the disease.
lung cancer (continued). "The significantly suppressive effect of miR‐206 on IL6‐induced gefitinib‐resistant EGFR‐mutant lung cancer cells prompted us to investigate its downstream signalling pathway." (PMID 31507089, 2019). "More importantly, the combination of EGFR drugs and integrin αvβ3 inhibitors revealed superior anti-cancer effects, which provides a feasible approach in clinical lung cancer treatment." (PMID 31316001, 2019). "Our data suggest that suppression of EGFR by miRNA-125a-5p can effectively trigger apoptosis and overcome EGFR-TKs resistance of lung cancer cells." (PMID 31759360, 2019). "LHRH-NLC-siRNAs-TAX nanoparticles were synthesized, characterized and tested in vitro using human lung cancer cells with different sensitivities to gefitinib (inhibitor of EGFR) and in vivo on an orthotopic NSCLC mouse model." (PMID 31754402, 2019). "The present study demonstrated that STAT3 promotes HER3 expression through the activation of G9a, which, in turn, represses HER3-targeted miR-145-5p expression in EGFR-positive lung cancers." (PMID 31619200, 2019). "According to previous studies, acetylcholine promoted lung cancer cell proliferation and migration through the mAChR3-activated EGFR/PI3K/Akt pathway accompanied by partial MMP activation." (PMID 30925742, 2019). "For example, patients that present with mutant KRAS nonsmall cell lung cancer have been well documented to be unresponsive to EGFR tyrosine kinase Inhibitor (TKI) therapy." (PMID 30941175, 2019). "GLK transgene does not initiate tumorigenesis in mice; however, GLK transgene promotes distant cancer metastasis in a genetically modified lung cancer mouse model—lung-specific EGFR-deletion mutant transgenic mouse line (EGFRdel Tg)." (PMID 31640697, 2019). "In particular, lung cancer is a prototype of precision oncology, and once a diagnosis of lung cancer is made, it is easier to develop effective treatment strategies using EGFR-TKI or anti-PD-1 antibodies as indicated by the tumor biomarkers." (PMID 30999697, 2019). "Several genes related to lung cancer were identified, such as epidermal growth factor receptor (EGFR) and ALK." (PMID 31508359, 2019). "In this study, we evaluated the IdyllaTM platform for EGFR testing in a representative range of lung cancer histopathology FFPE specimens." (PMID 30470932, 2019). "The emergence of EGFR-tyrosine kinase inhibitors (TKIs) for the treatment of lung cancer has significantly changed the therapeutic landscape of NSCLC in the past few decades." (PMID 31699150, 2019). "BBI608, a STAT3 inhibitor, reduced not only the viability of EGFR-positive lung cancer cell lines but also the expression of G9a and HER3." (PMID 31619200, 2019). "A review of literature was performed with "miliary intrapulmonary carcinomatosis", "lung cancer miliary", "pulmonary nodule, lung cancer" and "EGFR miliary" as key words in PubMed, Wangfang datebase and CNKI." (PMID 31874677, 2019). "Using the cancer cells of lung cancer, pancreatic cancer, and glioblastoma, the combinational effects of spironolactone with gemcitabine and osimertinib, a third-generation EGFR-TKI, were examined in vitro with cell viability assays." (PMID 31614999, 2019). "Based on the results, the National Comprehensive Cancer Network (NCCN) guidelines included osimertinib as a first-line treatment option, particularly in patients with EGFR mutant lung cancer." (PMID 30625213, 2019). "EGFR mutant lung cancer cell lines treated with gefitinib developed drug tolerance persisters (DTPs) characterized by increased senescence (CD133 low) and stemness (marked by CD133 high population)." (PMID 31731424, 2019).
lung cancer (continued). "EGFR is a protein that is highly related to lung cancer, and is abundant in exosomes isolated from lung cancer cells, lung biopsies and plasma, thus making it the most powerful biomarker from the revealed candidates." (PMID 31686989, 2019). "Given current evidence and our observations, there are potentially different genetic modifiers in somatically EGFR-mutant lung cancers from their wild-type counterparts." (PMID 31703574, 2019). "The development of therapies targeting RTKs, particularly EGFR, has been of great significance for lung cancer treatment." (PMID 31083461, 2019). "Two previous studies demonstrated that miRNA-7 and miRNA-146a can suppress the expression of EGFR gene and increase the sensitivity of the lung cancer cells to EGFR-TKIs." (PMID 31554377, 2019). "The development of TKI resistance is the main limiting factor of this otherwise effective target therapy in patients affected by EGFR-mutant lung cancer." (PMID 32082304, 2019). "Our data demonstrated that overexpressed SCD1 in lung cancer cells is a disadvantage for EGFR-targeting cancer therapy of NSCLC." (PMID 31019378, 2019). "MiRNA-125a-5p was known as tumor suppressor that inhibits the expression of EGFR and downstream genes involved in EGFR signaling pathway, leading to inhibition of invasion and migration of lung cancer cells." (PMID 31759360, 2019). "Using the EGFR lung cancer model as an example, hyperactivation of the MET pathway either by amplification or by increased receptor protein expression and phosphorylation accounts for 5–10% of all patients resistant to EGFR-TKIs." (PMID 31815659, 2019). "All patients started having EGFR-TKI (afatinib, erlotinib, gefitinib or osimertinib) once the diagnosis of stage IIIB or IV lung cancer with EGFR mutation was established." (PMID 31728013, 2019). "Autophagy inhibition overcomes the resistance to EGFR inhibitors in lung cancer cells via Foxo3a activation or ER-stress, leading to apoptosis." (PMID 31514441, 2019). "Another study showed that a combination of SAHA and tyrosine kinase inhibitors (afatinib and WZ4002, third generation of TKIs) overcame EGFR TKI resistance in lung cancer cells and decreased cell viability both in vivo and in vitro." (PMID 31320814, 2019). "Combining all evidence, we established a relationship between BZW1 and EGFR in lung cancer metastasis." (PMID 31601833, 2019). "In both EGFR-TKI-sensitive lung cancer cell lines used in the present study, treatment with serum from smokers resulted in a significant inhibition of the effects of erlotinib, compared with serum from a non-smoker." (PMID 30818860, 2019). "Because there was no change in the expression of HER2 in A549shG9a, we concluded that STAT3 was a potential therapeutic target against lung cancers with EGFR-TKI resistance that was superior to G9a." (PMID 31619200, 2019). "Blood was collected from nine patients upon the diagnosis of lung cancer and 34 patients after EGFR-TKI therapy." (PMID 31185703, 2019). "Zalutumumab, an IgG1 anti-EGFR mAb, can inhibit ligand binding, EGFR signaling, and the metastatic potential of lung cancer cells." (PMID 31527477, 2019). "Resistance to the new generation EGFR-TKI, Osimertinib, can emerge in patients with EGFR-mutated lung cancer." (PMID 30651547, 2019). "Here, we presented an EGFRL858R/T790M/FGFR1 dual-inhibitor 15c, which can simultaneous inhibited the kinase activity of EGFRL858R/T790M and FGFR1 both in kinase assay and cell study, for the treatment of FGFR1-amplified EGFR-TKIs resistant lung cancers." (PMID 31998131, 2019). "Activation of IGF-1 receptor (IGF-1R) signaling confers resistance to afatinib in EGFR T790M-mutant lung cancer cells." (PMID 30609749, 2019). "The poor clinical response of lung cancer cells to anti-EGFR therapies is due to the primary and secondary resistance of NSCLC cells to these drugs." (PMID 31554377, 2019).
lung cancer (continued). "Lung cancer is a genetically heterogeneous disease, and in lung adenocarcinoma, K-RAS and epidermal growth factor receptor (EGFR) are most commonly activated by mutations." (PMID 30754676, 2019). "Mutations in epidermal growth factor receptor (EGFR), and rearrangements of anaplastic lymphoma kinase (ALK) are targetable in lung cancer, while BRAF mutations have been successfully targeted in metastatic melanoma." (PMID 30886831, 2019). "A recent investigation showed that the nuclear accumulation of IGF1R in lung cancer contributed to EGFR-TKIs resistance observed in vivo and in vitro." (PMID 30823937, 2019). "Approximately 50% of lung cancer patients possess epidermal growth factor receptor (EGFR) overactivated." (PMID 31636509, 2019). "Clinical trials for the combination of EGFR TKIs and nivolumab in EGFR mutant lung cancer have delivered promising results." (PMID 30621125, 2019). "In subsequent studies, they found GSDMD induced lung cancer proliferation and poor prognosis through EGFR/AKT signaling pathway." (PMID 31616642, 2019). "MiR-205 depletion releases the ZEB1 and SRC suppression (as both are miR-205 targets) and induces EGFR tyrosine kinase inhibitor resistance in EGFR mutant lung cancer." (PMID 30813457, 2019). "In the present study, we examined the effect of miRNA-145 on EGFR expression, cell growth and sensitivity of lung cancer cells to erlotinib." (PMID 31554377, 2019). "In this study, we aimed to explore EGFR knockout as a therapeutic option in EGFR wild-type and KRAS mutated lung cancer cells." (PMID 30935067, 2019). "EGFR amplification is also frequently found in many cancers such as lung cancer, breast cancer, and glioblastomas." (PMID 31159251, 2019). "For example, tyrosine kinase inhibitors (TKIs), designed to target mutant EGFR, have shown dramatic therapeutic efficacy in lung cancer; however, patients often develop resistance to therapy." (PMID 31235851, 2019). "Rapid developments in molecular biology provide the evidence that driver mutation, such as epidermal growth factor receptor (EGFR) and anaplastic lymphoma kinase (ALK) genes, play an important role in the oncogenesis of non–small cell lung cancer (NSCLC)." (PMID 30609789, 2019). "Thus, there may be a genetically definable subset of lung cancer patients harbouring germline mutations involved in the dysfunction of DNA repair system, where genomic instability may be a potential risk modifier for EGFR mutation in lung tumour." (PMID 31703574, 2019). "TargomiR uses miR-16 for its tumor-suppressive function and an EGFR antibody as a targeting moiety to consistently target deregulated lung cancer cells." (PMID 31717435, 2019). "Recently, targeted therapy such as tyrosine kinase inhibitors (TKIs) for EGFR (epithelial growth factor receptor) has improved the clinical management of lung cancer." (PMID 31043584, 2019). "Epidermal Growth Factor Receptor (EGFR) expression, for instance, together with EGFR mutation status can be used to predict response to existing anti-EGFR treatments in patients with lung cancers." (PMID 30838036, 2019). "Mutations in the EGFR gene cause autosomal recessive neonatal inflammatory skin and bowel disease-2 (NISBD2, OMIM#616069) and lung cancer (OMIM#211980)." (PMID 30678103, 2019). "In spite of this, there are clear indications that a subset of patients with EGFR mutant lung cancer benefit from these therapies." (PMID 31291990, 2019). "The potent effects of miR‐206 in reducing the IL6‐induced gefitinib resistance in EGFR‐mutant lung cancer prompted us to explore the direct downstream effector of miR‐206." (PMID 31507089, 2019). "In total, 80 cases were confirmed to be stage III or IV lung cancer patients that had received 1st line chemotherapy (19 were excluded because of EGFR/ALK positivity)." (PMID 31744064, 2019).
lung cancer (continued). "To address these issues, we utilized a previously developed immunocompetent mouse model of EGFR mutant lung cancer and tested the consequences of erlotinib or oncogene de-induction on the immune microenvironment." (PMID 31291990, 2019). "Lung cancers are frequently characterized by inappropriate activation of epidermal growth factor receptor (EGFR)-dependent signaling and epigenetic silencing of the NADPH oxidase (NOX) enzyme DUOX1, both potentially contributing to worse prognosis." (PMID 30890751, 2019). "Lung cancer was the most commonly reported neoplasm, and EGFR, KRAS, and ALK analysis using polymerase chain reaction or fluorescence in situ hybridization was achieved in 67%–100% of the specimens." (PMID 31179853, 2019). "In this study, we found that IGFBP7 contributes to resistance to EGFR-TKIs and showed that enhanced IGFBP7 expression promoted resistance to EGFR-TKI in lung cancer cells by mediating the IGF-1R pathway." (PMID 30609749, 2019). "With regard to EGFR inhibitors, two independent studies show profound reduction of fasting glucose levels and normalization of HbA1c in two lung cancer patients with T2D treated with the EGFR inhibitor erlotinib." (PMID 31676778, 2019). "Initially osimertinib was approved for the treatment of metastatic EGFR T790M mutant NSCLC, after the patient had progressed on first- or second-generation EGFR TKIs, however, it is now also used as a first-line treatment for EGFR mutant lung cancer patients." (PMID 31083461, 2019). "In lung cancer, high EGFR expression in EGFR wild-type patients was shown to be a positive predictive factor for erlotinib treatment." (PMID 31514305, 2019). "A recent study revealed that the median turnaround time for EGFR gene analysis in newly diagnosed lung cancer patients was three business days while using liquid biopsy and was twelve business days while using tissue biopsy." (PMID 31652678, 2019). "Beyond that, some research showed that the HDAC inhibitor suberoylanilide hydroxamic acid (SAHA) remarkably inhibited cell viability and proliferation, induced cell apoptosis in EGFR-mutant lung cancer cell lines." (PMID 31261881, 2019). "In conclusion, we demonstrated the STAT3-G9a-HER3 axis in lung cancer that evades EGFR-TKI therapies." (PMID 31619200, 2019). "We focused on the function of IL-22 in EGFR-TKI resistance and found that IL-22 expression was higher in lung cancer tissues and plasma of patients with EGFR-TKI acquired resistance." (PMID 31750252, 2019). "Consistent with the report that the expression of α3β1 integrin was increased in erlotinib-resistant NSCLC tumors, we found that LXY30 was the most prevalent and potent integrin ligand for binding to live EGFR-mutant lung cancer." (PMID 31182116, 2019). "Previously published results have shown that PKM2 can interact with mutant EGFR and HSP90 and prolonged the protein half-life of EGFR in lung cancer cells." (PMID 31120964, 2019). "BBI608, a STAT3 inhibitor, was a potential therapeutic agent that reduced the cell viability of EGFR-positive lung cancer cell lines." (PMID 31619200, 2019). "Integrins and EGFR share common downstream signaling pathways mediating the lung cancer initiation, growth, metastasis, and survival." (PMID 31182116, 2019). "Most case reports are from the EGFR-mutant lung cancer patients who are ethically treated with multiple biopsies." (PMID 31570104, 2019). "We herein found that the lung cancer cells with overexpressed SCD1 showed high resistance to EGFR inhibitor-induced cytotoxicity with high IC50 values than that with relatively low expressed SCD1." (PMID 31019378, 2019).
lung cancer (continued). "In sum, these data support that the intracellular IL‐6 serves as a direct target of miR‐206 in EGFR‐mutant lung cancer cells." (PMID 31507089, 2019). "Both of these genes are found on the short arm of Chromosome 7 where fifteen other transcriptionally dysregulated genes were identified suggesting the region is specifically important in EGFR activated lung cancer." (PMID 31857847, 2019). "In EGFR mutant lung cancer, loss of PTEN led to resistance to EGFR inhibitors such as erlotinib, because PI3K activation can somehow interconnect PI3K-AKT and MAPK pathways." (PMID 31795465, 2019). "Deletion in exon 19 and a single point mutation in exon 21 prompt the generation of EGFR tyrosine kinase inhibitor, results in exhaustive NSCLC cell proliferation, being the precursor for the spread of lung cancer cells in human." (PMID 31745155, 2019). "In this study, three lung cancer cell lines A549, HCC827 and H1975 were selected which represent wild type, EGFR mutant and EGFR mutant with a T790M mutation cell lines." (PMID 31486270, 2019). "Taken together, the results suggest a complex interaction between MET and EGFR in NSCLC in the presence of EGFR TKIs and provide unique insight into potential resistance mechanisms and management strategies in EGFR/METex14-altered lung cancers." (PMID 31157314, 2019). "This study is the first to describe the imaging differences between lung cancer patients with KRAS and EGFR mutations using DESCT according to our knowledge." (PMID 31783917, 2019). "When DZNep was combined with another HDAC inhibitor SAHA, it induced apoptosis in nonsmall cell lung cancer through the EGFR pathway in vitro and in vivo.Another strategy in epigenetic therapy is targeting BET bromodomain proteins." (PMID 31320814, 2019). "During their clinical development, however, EGFR inhibitors were also studied in combination with chemotherapy within the lung cancer setting." (PMID 31183252, 2019). "A complex composed of sortilin and two tyrosine kinase receptors containing TrkB and EGFR in exosome structure mediated communication and signaling events between the lung cancer cells and its target, the endothelial cells." (PMID 31908734, 2019). "While enhanced IGFBP7 expression promoted resistance to EGFR-TKIs in lung cancer cells, IGF-1R activation has been reported to confer acquired resistance to EGFR-TKIs." (PMID 30609749, 2019). "In summary, METex14 is a novel mechanism of acquired resistance to EGFR TKI therapy in EGFR-mutant lung cancer." (PMID 31157314, 2019). "In summary, we showed that radiosensitivity differences between EGFR mutant and wild-type lung cancer cells are larger at lower doses." (PMID 31349558, 2019). "EGFR tyrosine kinase inhibitors (EGFR-TKIs) are used for clinical treatment of such lung cancers, but acquired resistance often mitigates their efficacy." (PMID 31426517, 2019). "Ectopic expression of receptor tyrosine kinases (RTKs) has been proved to play a vital role in lung cancer, and recently, tyrosine kinase inhibitors targeting EGFR are hot spots of targeting therapy in variety of cancer types." (PMID 31579447, 2019). "Although targeted EGFR therapy has achieved significant success in treating epithelial cancers, such as lung cancer, its therapeutic effect on GBM has been disappointing." (PMID 31122294, 2019). "The distinct molecular subtypes of lung cancer are defined by monogenic biomarkers, such as EGFR, KRAS, and ALK rearrangement." (PMID 31480292, 2019). "Antitumor therapeutics by antibodies targeting HER3 triggers a response to EGFR-TKI erlotinib in refractory non–small-cell lung cancer." (PMID 31619200, 2019). "PLA has been used to quantify complexes of epidermal growth factor receptor (EGFR) with its adaptor protein growth factor receptor–bound protein 2 (GRB2) in human lung cancer samples, proving that this technique can be used in clinical settings." (PMID 31426445, 2019).